MAGEL2 (MAGE family member L2)
Description:
Probably enhances ubiquitin ligase activity of RING-type zinc finger-containing E3 ubiquitin-protein ligases, possibly through recruitment and/or stabilization of the Ubl-conjugating enzyme (E2) at the E3:substrate complex. Acts as a regulator of retrograde transport via its interaction with VPS35. Recruited to retromer-containing endosomes and promotes the formation of 'Lys-63'-linked polyubiquitin chains at 'Lys-220' of WASHC1 together with TRIM27, leading to promote endosomal F-actin assembly. Regulates the circadian clock by repressing the transcriptional activator activity of the CLOCK-BMAL1 heterodimer. Significantly promotes the cytoplasmic accumulation of CLOCK (By similarity).
Synonyms: NDNL1; nM15; PWLS; SHFYNG
Tractability: PROTAC: ubiquitination databases record sites on it.
Gene: Protein-coding gene on chromosome 15 (23,643,549 to 23,647,867, reverse strand). Ensembl gene ENSG00000254585.
Subcellular location: Early endosome; Cytoplasm; Nucleus
Gene Ontology:
Molecular function: protein binding; ubiquitin-protein transferase activity
Biological process: Arp2/3 complex-mediated actin nucleation; protein K63-linked ubiquitination; retrograde transport, endosome to Golgi; negative regulation of DNA-templated transcription; negative regulation of transcription by RNA polymerase II; regulation of circadian rhythm
Cellular component: endosome; retromer complex; cytoplasm; nucleus; cytosol; early endosome
Genetic constraint (gnomAD): Missense variants: 1,830 observed, 1,651.6 expected, observed/expected ratio (o/e) 1.11, 90% interval 1.07 to 1.15. Synonymous variants: 792 observed, 698.78 expected, observed/expected ratio (o/e) 1.13, 90% interval 1.07 to 1.2.
Gene-disease validity (ClinGen):
ClinGen rates the evidence that MAGEL2 causes each of these diseases.
Schaaf-Yang syndrome (autosomal dominant): Definitive.
Homologues: Orthologues: chimpanzee MAGEL2 (99% identical), dog MAGEL2 (81% identical), guinea pig MAGEL2 (73% identical), mouse Magel2 (65% identical), rat Magel2 (65% identical), zebrafish ndnl2 (8% identical), Drosophila melanogaster MAGE (5% identical). Paralogues in human: TRO (14% identical), MAGED4 (13% identical), MAGED4B (13% identical), MAGED2 (13% identical), MAGED1 (13% identical), MAGEE1 (11% identical), NSMCE3 (10% identical), MAGEA11 (10% identical), MAGEF1 (10% identical), NDN (9% identical), MAGEB4 (9% identical), MAGEB16 (9% identical), and 25 more.
Diseases named in the same sentence as MAGEL2 in open-access papers:
MAGEL2 is named in the same sentence as 54 diseases in open-access papers, as found by Europe PMC text mining. Sharing a sentence is not in itself a finding about the gene and the disease. The quoted sentences say what the papers report.
Prader-Willi syndrome (39 papers, 2009 to 2026). "Mutations within MAGEL2 from chromosomal region 15q11–q13 cause Schaaf-Yang syndrome, which is phenotypically related to Prader-Willi syndrome, caused by deletion of the SNORD116 cluster within the same locus." (PMID 38908375, 2024). "In the Magel2-deficient mouse, mouse models of Prader-Willi syndrome, the number of oxytocin neurons and the oxytocin receptor-expressing astrocytes were reduced in the PVN." (PMID 37175953, 2023). "The loss of MAGEL2 in neurons leads to aberrant endosomal protein trafficking and reduces the abundance of SG proteins, contributing to the etiology of Prader-Willi syndrome (PWS)." (PMID 37799273, 2023). "Prader-Willi Syndrome arises in part through loss of MAGEL2-regulated secretory granule biogenesis and neuropeptide production in the hypothalamus." (PMID 32879135, 2020). "Protein truncating mutations in MAGEL2 cause Schaaf-Yang syndrome, and MAGEL2 is one of a small set of genes deleted in Prader-Willi syndrome." (PMID 32315313, 2020). "Protein truncating mutations in MAGEL2 cause Schaaf-Yang syndrome, while loss of MAGEL2 and other contiguous genes causes Prader-Willi syndrome." (PMID 32315313, 2020). "As NRAGE is involved in the p75NTR mediated programmed cell death, MAGEL2 is linked to neurodevelopmental disorders such as Prader-Willi syndrome and Schaaf-Yang syndrome." (PMID 32917932, 2020). "Mutations of the Magel2 gene have been described in patients with autism and a loss of Magel2 is also associated with Prader-Willi syndrome." (PMID 30057594, 2018). "In this regard, some of the main features of the Alx3-deficient mice phenotype including increased adiposity, decreased lean mass and decreased food intake are similar to those observed in mice deficient for Magel2, a gene whose mutations are associated with Prader-Willi syndrome in humans." (PMID 39129011, 2024). "Furthermore, the G6PDS188F variant increased Magel2 – a gene encoding circadian clock-related protein that suppresses obesity associated with Prader-Willi syndrome – and reduced HFD-induced non-alcoholic fatty liver." (PMID 38876306, 2024). "PofOm enrichment at SoC-CpGs is driven by a large PofOm region spanning 6 CpGs on chr15 at IGF1R; along with two singleton PofOm SoC-CpGs, one on chr18 close to PARD6G and the other in the Prader-Willi syndrome-associated imprinted region neighbouring MAGEL2, also on chr15." (PMID 35188105, 2022). "We propose that disruption of circadian rhythm in people with Prader-Willi syndrome may be caused by MAGEL2-dependent deficiencies in the ubiquitin-dependent regulation of CRY1 levels." (PMID 32315313, 2020). "We propose that loss of the MAGEL2 gene in people with Prader-Willi Syndrome may cause deficient leptin sensing, leading to the increased appetite and obesity that are hallmarks of this genetic condition." (PMID 23341784, 2013). "In Prader-Willi Syndrome, loss of MAGEL2 may likewise abolish leptin responses in POMC hypothalamic neurons." (PMID 23341784, 2013). "The role of MAGEL2 in melanocortin-associated neuronal pathways may provide important insights into dysfunctional ingestive behavior and obesity in Prader-Willi syndrome." (PMID 23341784, 2013). "Prader-Willi syndrome (PWS) arises from the loss of expression of 7 contiguous paternally inherited genes located in the 15q11-q13 region, including the MAGEL2 and NECDIN genes." (PMID 40048253, 2025). "Previous studies into the consequences of MAGEL2 deficiency have focused on its complete loss of function, as MAGEL2 is also a gene frequently deleted in patients with Prader-Willi syndrome (PWS; OMIM #176270)." (PMID 36637363, 2023). "Prader-Willi syndrome (PWS) is a developmental disorder caused by loss of maternally imprinted genes on 15q11-q13, including melanoma antigen gene family member L2 (MAGEL2)." (PMID 32879135, 2020).
Prader-Willi syndrome (continued). "Although MAGEL2 is deleted in most cases of Prader-Willi syndrome (PWS, OMIM #176270), SYS presents with more severe symptoms, suggesting pathogenic effects of truncated MAGEL2 beyond a mere loss of function." (PMID 41168328, 2025). "Although G6PDS188F variant did not prevent the loss of HFD-induced Bmal1 expression, intriguingly it increased Magel2, a circadian clock-controlled gene whose disruption results in some of the characteristics of Prader-Willi Syndrome." (PMID 38876306, 2024). "As a key Prader-Willi syndrome gene, mice null for paternal Magel2 have been extensively characterised, with phenotypes seen in metabolism, feeding, and several deficits in neonates including suckling and USV production." (PMID 37856383, 2023). "Interestingly, 4 SYS patients with truncated mutations in paternal copies of MAGEL2, who were reported for the first time in 2013, were initially considered to be patients of the “Prader-Willi syndrome (PWS)”." (PMID 34128869, 2021). "Excessive daytime sleepiness, night-time or early morning waking, and narcoleptic symptoms are seen in people with Prader-Willi syndrome and Schaaf-Yang syndrome, while mice carrying a gene-targeted Magel2 deletion have disrupted circadian rhythms." (PMID 32315313, 2020). "Pathogenic variants in the paternal copy of MAGEL2 cause Schaaf-Yang syndrome (SHFYNG), a neurodevelopmental disorder related to Prader-Willi syndrome (PWS)." (PMID 31685878, 2019). "We sequenced MAGEL2 in patients suspected Prader-Willi syndrome (PWS) to delineate clinical presentation of SYS." (PMID 31791363, 2019). "Inactivation of the mouse MAGEL2 alone was shown to lead to abnormalities suggestive of hypothalamic dysfunction similar to the Prader-Willi Syndrome." (PMID 24558400, 2014). "MAGEL2 is one of several genes typically inactivated in the developmental obesity disorder Prader-Willi syndrome (PWS)." (PMID 19172181, 2009). "Social deficits linked to autism spectrum disorders (ASDs) are reported in human carriers of de novo point mutations in the MAGEL2 gene, who develop Schaaf-Yang syndrome, and are also reported in patients with chromosomal alterations including MAGEL2, who develop Prader-Willi syndrome." (PMID 39423809, 2024). "This is observed in mouse KO models of the imprinted Magel2 gene that map to the Prader Willi syndrome (PWS) region, recapitulating some features of PWS patients, who after a failure to thrive as young infants exhibit a catch-up phase leading to overweight and hyperphagia." (PMID 35049495, 2022). "These mice lack Magel2, a gene contained in the Prader-Willi Syndrome (PWS) locus, an imprinted chromosomal region also known as “PWS paternal-only expressed region”." (PMID 36998737, 2023). "Prader-Willi syndrome (PWS) is a rare imprinting-related neurodevelopmental disorder caused by loss of paternally expressed genes within the chromosome 15q11-q13 region, including SNORD116, MAGEL2, and NDN." (PMID 41677631, 2026). "Given that anxiety is a prominent phenotypic behavior in PWS, we investigate the role of the Magel2 gene, particularly in hypothalamic POMC neurons innervating the medial amygdala (MeA), in the behavioral phenotypes associated with Prader-Willi Syndrome (PWS)." (PMID 41321745, 2025). "Within this shared run, four genes were detected: IGHM (Immunoglobulin heavy constant Mu), MKRN3 (Makorin finger protein 3), MAGEL2 (MAGE family member L2) and NDN (Necdin), located upstream of the Prader-Willi syndrome (PWS) region." (PMID 34695128, 2021). "Deletion of genes from this region inherited from the father (MKRN3, MAGEL2, NDN, SNURF-SNPRN genes) leads to Prader-Willi syndrome (PWS)." (PMID 33375093, 2020). "MKRN3, MAGEL2 and NDN are three protein-coding genes located in the human 15q11-13 imprinted region, and the absence of the paternal contribution of this chromosomal region could lead to human Prader-Willi syndrome, characterized by neurogenetic disorders." (PMID 34359112, 2021).
Prader-Willi syndrome (continued). "Deficiencies of other imprinted genes in the region, including MKRN3, MAGEL2 and/or NDN apparently play a role but not sufficient alone to generate the cardinal features recognized in Prader-Willi syndrome." (PMID 22043168, 2011).
Schaaf-Yang syndrome (36 papers, 2016 to 2026). "Truncating variants in the paternal copy of MAGEL2, on the other hand, cause Schaaf-Yang syndrome (SYS), a rare neurodevelopmental disorder diagnosed in over 250 individuals to date." (PMID 41168328, 2025). "Deletion of MAGEL2 is linked to Schaaf-Yang syndrome, which is characterized by a unique skeletal phenotype with abnormal BMD due to increased OCs activity and enhanced transformation of OBs into adipocytes." (PMID 38737552, 2024). "In contrast to PWS, Schaaf-Yang syndrome (SYS) is caused solely by truncating mutations of this MAGEL2 gene." (PMID 39609859, 2024). "Inactivating mutations in MAGEL2 cause Schaaf-Yang syndrome (MIM: 615547), which is characterized by delayed psychomotor development, frequent intellectual disability, hypotonia, feeding difficulties, and various dysmorphic facial features." (PMID 38737552, 2024). "Remarkably, Schaaf-Yang syndrome (SYS) is also characterized by nonsense mutations in the MAGEL2 gene." (PMID 37491450, 2023). "Truncating variants in MAGEL2, one of the paternally expressed genes in this region, were shown to induce Schaaf-Yang syndrome (SYS, OMIM #615547)." (PMID 36836222, 2023). "We report the generation, molecular validation and phenotypic characterization of a novel rat model with a truncating Magel2 mutation modeling variants associated with Schaaf-Yang syndrome-causing mutations." (PMID 36637363, 2023). "Here we provide the first experimental evidence that newborn harboring deletion in Magel2, an autism associated-gene implicated in Prader-Willi and Schaaf-Yang syndromes, exhibit atypical thermosensory behavior during the first postnatal week." (PMID 35396500, 2022). "These include disorders such as Schaaf-Yang syndrome (MAGEL2), which had only one variant in our cohort, or HNRNPH2-related NDD, which had no variants in our cohort." (PMID 36359385, 2022). "Schaaf-Yang syndrome (SYS) is a rare neurodevelopmental disorder caused by pathogenic variants in the MAGEL2 gene." (PMID 35047255, 2021). "The Schaaf-Yang syndrome (SYS) is an autosomal dominant multi-system genetic disease caused by melanoma antigen L2 (MAGEL2) gene mutations imprinted by mothers and expressed by fathers on the 15q11–15q13 chromosomes in the critical region of Prader-Willi." (PMID 34128869, 2021). "The MAGEL2-associated Schaaf-Yang syndrome (SHFYNG; OMIM #615547, ORPHA: 398069) is a rare hereditary neurodevelopmental disorder (prevalence < 1/1,000,000) with a profound impact on global development." (PMID 33076953, 2020). "Schaaf-Yang syndrome (SYS) is a neurodevelopmental disorder caused by truncating variants in the paternal allele of MAGEL2, located in the Prader-Willi critical region, 15q11-q13." (PMID 32804975, 2020). "In 2013, the first four individuals with truncating variants in the paternal allele of MAGEL2 were reported, and later described as having Schaaf-Yang syndrome (SYS, OMIM#615547)." (PMID 32804975, 2020). "Mutations in the MAGEL2 gene alone cause Schaaf-Yang syndrome, a disorder with overlapping phenotypes with PWS." (PMID 32315313, 2020). "Our results indicate that MAGEL2 variants can cause congenital heart disease and fatal respiratory complications, broadening the phenotypic spectrum and adding to the fatal cases of Schaaf-Yang syndrome." (PMID 32702813, 2020). "Schaaf-Yang syndrome, a rare imprinted hereditary disease caused by MAGEL2 variants, manifests as developmental delay/intellectual disability, neonatal hypotonia, feeding difficulties, contractures, and autism spectrum disorder." (PMID 32702813, 2020). "Of the PWS locus genes, MAGEL2 is particularly interesting given that paternal, de novo mutations of MAGEL2 cause the PWS-related disorder Schaaf-Yang syndrome (SYS; OMIM #615547)." (PMID 32879135, 2020). "Truncating disease causing variants of the imprinted MAGEL2 gene on 15q11q13 have been described in patients with Schaaf-Yang syndrome (#615547)." (PMID 31235867, 2019).
Schaaf-Yang syndrome (continued). "It was recently reported that Chitayat-Hall syndrome was also caused by pathogenic variants in MAGEL2." (PMID 31791363, 2019). "It was recently reported that truncating variants in MAGEL2, one of the paternally expressed genes located in this region, caused Schaaf-Yang syndrome (SYS, OMIM #615547)." (PMID 31791363, 2019). "Since the initial identification of truncating point mutations in MAGEL2 leading to Schaaf-Yang syndrome, two more studies have identified additional individuals with MAGEL2 point mutations." (PMID 28933382, 2016). "Both PWS and MAGEL2-associated Schaaf-Yang syndrome manifest clinical phenotypes that overlap, and Schaaf-Yang syndrome should be considered an important differential diagnosis of PWS, in particular in the newborn period." (PMID 28933382, 2016). "The loss of MAGEL2 ultimately leads to insufficient F-actin nucleation and a decreased percentage of SG proteins recycled, which manifests in a perturbation of the hormonal secretion in patients with Prader-Willi and Schaaf-Yang syndromes." (PMID 37799273, 2023). "Schaaf-Yang syndrome (SYS) (OMIM 615547) is an autosomal dominant multi-system genetic disease caused by Melanoma antigen L2 (MAGEL2) gene mutations imprinted by mothers and expressed by fathers on 15q11–15q13 chromosomes in the critical region of Prader-Willi." (PMID 34128869, 2021). "In summary, mutations in MAGEL2 (in Schaaf-Yang syndrome) or loss of MAGEL2 function (in PWS) could result in the circadian rhythm and sleep disruptions through disruption of the ubiquitin-dependent feedback loops that regulate circadian rhythm." (PMID 32315313, 2020). "Clinical features and MAGEL2 variants in fatal cases of Schaaf-Yang syndrome." (PMID 32702813, 2020). "Recently, pathogenic variants in MAGEL2 were reported as causes of Chitayat-Hall syndrome, which is characterized by distal arthrogryposis, intellectual disability, dysmorphic features and hypopituitarism, and in particular, growth hormone deficiency (OMIM #208080)." (PMID 31791363, 2019). "Notably, 2 cases were found with truncating variants in MAGEL2 gene and were finally diagnosed as Schaaf-Yang syndrome." (PMID 29581464, 2018). "MAGEL2-associated Schaaf-Yang syndrome (SHFYNG, OMIM #615547, ORPHA: 398069), which was identified in 2013, is a rare disorder caused by truncating variants of the paternal copy of MAGEL2, which is localized in the imprinted region on 15q11.2q13." (PMID 33076953, 2020). "Recently, mutations in MAGEL2 have been described in Schaaf-Yang syndrome (SHFYNG) and in severe arthrogryposis." (PMID 28281571, 2017). "This cluster comprises the MKRN3, NDN, MAGEL2, and SNHG14 genes, the loss of function of which contributes to Prader-Willi and Schaaf-Yang syndromes." (PMID 40877933, 2025). "Schaaf-Yang syndrome (SYS, OMIM #615547) is a rare neurodevelopmental disorder caused by truncating variants in the maternally imprinted MAGEL2 gene." (PMID 41168328, 2025). "One patient had pathogenic variants in MAGEL2 and CHRND, which are diagnostic for Schaaf-Yang syndrome and congenital myasthenic syndrome, respectively." (PMID 37989827, 2024). "MAGEL2 encodes the L2 member of the melanoma-associated antigen gene (MAGE) protein family, truncating mutations of which can cause Schaaf-Yang syndrome, an autism spectrum disorder." (PMID 34265304, 2021). "Whole-exome sequencing showed a heterozygous variation in the MAGEL2 gene, NM_019066.4:c.1687C > T (p.Q563X) and diagnosed as Schaaf-Yang syndrome." (PMID 34128869, 2021). "Schaaf-Yang syndrome (OMIM #615547) is a PWS-like disease, due to truncating mutations in the MAGEL2 gene, which is located in the PWS critical region (chromosome 15q11-q13) and is normally maternally imprinted and paternally expressed." (PMID 30968677, 2020). "Schaaf-Yang syndrome (SYS) is a newly recognized imprinting related syndrome, which is caused by a truncating variant in maternally imprinted MAGEL2 located in 15q11-q13." (PMID 31791363, 2019).